IL6 (interleukin 6)
Diseases named in the same sentence as IL6 in open-access papers (continued):
Sharing a sentence is not in itself a finding about the gene and the disease.
autoimmune disease (continued). "For example, B cell activating factor (BAFF) and IL-6 are elevated in SLE and other autoimmune diseases." (PMID 24180594, 2013). "Previously, IL-17 has been reported to stimulate production of IL-6 and STAT3 activation in inflammatory cells and fibroblasts in an autoimmune disease, as well as in cancer cells." (PMID 22171994, 2011). "However, in a proinflammatory environment, as observed in a mouse model of autoimmune disease, primary biliary cholangitis, Man impairs the production of TNF‐α, IL‐1β, Arg1, and IL‐6 cytokines." (PMID 39950558, 2025). "Furthermore, moderate exercise has anti-inflammatory effects in various diseases, and meta-analyses have shown that regular exercise can reduce levels of inflammation-related markers in autoimmune diseases, such as C-reactive protein, TNF-α, and IL-6." (PMID 41347064, 2025). "Another example is IL-6 that advances cancer cell survival, production, and immune resistance through the activation of STAT3 signaling routes and elicits persistent inflammation and autoimmunity by overproducing IL-6 in autoimmune disorders." (PMID 41465368, 2025). "IL-6 induction affects pathophysiology of major non-infectious kidney disorders including renal complication of autoimmune diseases, AKI, CKD, and rejection of renal allografts." (PMID 39723211, 2024). "There are scattered reports of increased blood levels of inflammatory cytokines (e.g., TNF-α and IL-6) in patients with sarcopenia in comparison to those without sarcopenia, suggesting a close relationship between sarcopenia and autoimmune diseases." (PMID 39600735, 2024). "However, SCUBE1, IL-6, and IMA can be raised in other pathologies, especially chronic inflammatory and autoimmune diseases." (PMID 39519217, 2024). "The loop involving B cells and plasma cells in the production of pro-inflammatory cytokines (IL-6 and TNF-α) and auto-antibodies, which can form immune complexes or bind directly to tissues, contributes to the development of autoimmune diseases, including thyroiditis and skin conditions." (PMID 39337081, 2024). "These compounds effectively intervene in the overactive inflammation and immune responses characteristic of rheumatic and autoimmune diseases by modulating various signaling pathways, including the TNF, Toll-like, IL-6, RANKL, MAPK, PI3K/AKT/mTOR, JAK/STAT, and NRF2/GPX4 pathways." (PMID 39524446, 2024). "The presence of interleukin-6 (IL-6) response elements in the LPA gene suggests that Lp(a) may act as an acute phase reactant in inflammatory conditions, including autoimmune diseases and myocardial infarction (MI)." (PMID 38542510, 2024). "In autoimmune diseases, GPNMB has anti-inflammatory properties, primarily exhibited in macrophages, where it suppresses the production of pro-inflammatory cytokines such as IL-6 and IL-12p40." (PMID 39263169, 2024). "Moreover, the secretions of IL-6 and TNF-α played a role in the development of fatigue in both autoimmune and non-autoimmune diseases via neuroinflammation and neuroprogressive changes." (PMID 38903826, 2024). "While IL-6 expression in VR increases, in parallel with IL-10 suppress EAO development, it can reduce TGC-induced EAO, and triggers apoptosis of germ cells within seminiferous tubules, known to exert opposite effects in autoimmune diseases." (PMID 37048754, 2023). "However, Th 17 cells and their related cytokines, such as IL-6, IL-10, IL-17 and TNF-α, are important inflammatory mediators in autoimmune diseases, including uveitis, and are thought to drive intraocular inflammation." (PMID 38351911, 2023). "In the event of infection, patients with autoimmune diseases have dysregulated innate and acquired immune responses that lead to overproduction and overresponse, mediated by pro-inflammatory cytokines such as TNF-α, IL-6, IL-Iβ, IL-17, and IL-18." (PMID 37104352, 2023).
autoimmune disease (continued). "Bearing in mind the different implications of IL-6 expression in the pathogenesis of RA and SLE and, therefore, that this was only an attempt to partially represent autoimmune diseases in general, these results were confirmed by combining RA and SLE patients into a unique cohort." (PMID 38003490, 2023). "Previously, it was shown that levels of TGF-β or IL-6 control the balance between TH17 and Treg cells, and their imbalance in favor of the former will break the immune homeostasis in the host and result in the development of autoimmune diseases." (PMID 36817487, 2023). "Women with PCOS tend to have inadequate progesterone secretion, estrogen increases IL-6 expression in T cells, and the absence of progesterone suppression may lead to overstimulation of the immune system, making these patients more susceptible to autoimmune diseases." (PMID 37215125, 2023). "Biologics are used to treat many different autoimmune diseases by targeting inflammatory cytokines (TNF-α and IL-6) and cytokine receptors, interrupting the inflammatory vicious cycle, and are recommended even in early RA with low-severity inflammatory arthritis." (PMID 37763669, 2023). "Moreover, psoriasis is characterized by increased expression of TNF-α and IL-6 in lesions, and TNF-α is a verified drug target in psoriasis and other autoimmune diseases, such as inflammatory bowel disease (IBD) and RA." (PMID 36110097, 2022). "Deceased patients respond to higher HERV-K levels increasing IL-17, a further proinflammatory mediator that may upregulate IL-6, CRP, and airway remodeling and is upregulated by HERVs in autoimmune diseases." (PMID 35459226, 2022). "The toxic targets of LGT were mainly distributed in the downstream of the pathways, such as LCN2, IL6, IL1B, and CSF3, and ultimately target the inflammatory host defense autoimmunity, proinflammatory activities and other inflammatory reactions and autoimmune diseases." (PMID 36339610, 2022). "Studies investigating its regulatory role on inflammatory markers such as IL-6, IL-17 and TNF-α, suggest that PGZ may be an effective candidate for autoimmune diseases and inflammatory skin disorders." (PMID 36429011, 2022). "While alternative signaling was possible in our trial, it does not reconcile the efficacy of tocilizumab in other autoimmune diseases, where similar changes in serum IL-6 and sIL-6R have been reported." (PMID 34747368, 2021). "However, it is essential to recall that pediatric autoimmune diseases treated with tocilizumab, like systemic JRA, have robust translational and clinical research to support IL-6 as the main inflammatory promotor." (PMID 34869111, 2021). "Five of the 10 patients with a high IL-6 who were still alive and without disease recurrence at the study closure, had either a second primary cancer or an autoimmune disease at diagnosis." (PMID 32621022, 2021). "Under inflammatory conditions, such as autoimmune diseases and allergy, it has been shown that several cytokines (IL-4, TNF-α, and IL-6) may be involved in downmodulation of Treg suppression." (PMID 34777330, 2021). "In some situations, Treg defects can be reversed by successful treatment of autoimmune disease, particularly RA, by neutralization of cytokines (such as TNF or IL-6) that can impair Treg differentiation and/or functional effectiveness, but similar studies have not been reported in SSc." (PMID 33407866, 2021). "Patients with autoimmune diseases on anti-TNF have had reduced serum levels of TNF-α and IL-6." (PMID 33995033, 2021). "Moreover, several previous studies have illustrated that activated NF-κB regulates the expression of genes such as IL-1β, IL-6, and TNF-α and promotes the occurrence, development and pathogenesis of autoimmune diseases, chronic infections and cancer." (PMID 34017253, 2021).
autoimmune disease (continued). "Furthermore, disruption of Rubicon leads to upregulation of IL‐1β, IL6 and TNF‐α secretion, and the mice fail to gain weight and develop an autoimmune disease that resembles systemic lupus erythematosus." (PMID 33586810, 2021). "In autoimmune disease, dendritic cells play an indisputable role in instructing the polarization of CD4+ Th17 cells in immune response through generation of cytokines such as IL-6, IL-23, and IL-1β." (PMID 33643041, 2020). "At least, IL-2, IL-6, TNF-α, IFN-γ were produced when co-cultures of CII-CAR-T cells and fresh cartilage, and these cytokines also play roles in the occurrence and development of inflammatory arthritis and other autoimmune diseases." (PMID 33343563, 2020). "In addition, adipocytes secrete various cytokines, such as leptin, adiponectin, IL-6, resistin, visfatin and TNF-α, which regulate the proliferation and differentiation of T cells and are involved in many chronic inflammatory and autoimmune diseases." (PMID 33329579, 2020). "Additionally, IL-6 inhibits the production of T regulatory T CD4+CD25+ FOXP3 cells, therefore attributing to the development of a long list of autoimmune diseases." (PMID 32961074, 2020). "RA is an autoimmune disease in which osteochondral destruction occurs with the increased expression of RANKL and MMPs from synovial tissues by excessive inflammatory cytokines such as TNF-α and IL-6." (PMID 31698687, 2019). "Recent studies reported that Th17 cells induced mainly by IL-6 and TGF β are effective at sites of extracellular parasitic bacteria and mucosa immunity but do not appear to cause autoimmune diseases accompanied by chronic inflammation." (PMID 28316374, 2017). "Both IL-6 and soluble IL-6R are commonly upregulated in patients and autoimmune diseases, which are driven by IL-6 trans-signaling rather than classic signaling." (PMID 26270565, 2015). "This may explain the correlation between serum CRT levels and autoimmune disorders, since TNF-α and IL-6 represent predominant inflammatory cytokines released by activated macrophages." (PMID 24566135, 2014). "This promising strategy has not been used so far for IL-6 but has been successfully established for other cytokines, including tumor necrosis factor-alpha (TNFα) and IL-1β and IL-23 in different autoimmune diseases." (PMID 25059342, 2014). "The effect of marine-derived n-3 PUFAs from dietary intake on CRP, IL-6 and TNF-α was only assessed in subjects with chronic non-autoimmune disease, and significant lowering effect was only observed on IL-6, but not on CRP and TNF-α." (PMID 24505395, 2014). "The effect of marine-derived n-3 PUFAs from dietary intake was only assessed in subjects with chronic non-autoimmune disease, and a significant lowering effect was observed on IL-6, but not on CRP and TNF-α." (PMID 24505395, 2014). "Besides the importance of IL-6 in EAE and its link to the pathogenesis of various other autoimmune disorders, influence of IL-6 on MS is controversially discussed." (PMID 24155968, 2013). "Similarly if we consider that the key function of IL-6 is the homeostasis within the Th cell differentiation in Treg or Th17 cells, it is clear why women are more susceptible to diseases characterized by a lack of regulatory cell functionality such as autoimmune diseases." (PMID 22235223, 2011). "Decreased levels of proinflammatory cytokines IL-6, IL-12 and TNF-α do not easily explain the symptoms of autoimmune diseases observed in DC-STAMP-deficient mice." (PMID 21978263, 2011). "These targeted therapies, including anti-TNF, anti-IL-6, and anti-CD20 agents, are essential in autoimmune disease management and may provide disease stabilization without significant risk of autoimmune disease activation." (PMID 40461909, 2025).
autoimmune disease (continued). "Furthermore, IL-6 exhibits substantial diurnal variation and is influenced by multiple non-infectious conditions (e.g., trauma, malignancy, autoimmune disease), potentially limiting specificity in undifferentiated critically ill patients." (PMID 41439926, 2025). "This suggests that, even when the autoimmune disease is well controlled and ocular symptoms may not be severe, IL-6 serves as an indicator of ongoing ocular surface inflammation and damage." (PMID 40095800, 2025). "B cells are important effector cells that are involved in the pathogenesis of autoimmune diseases through the production of auto-antibodies, the promotion of CD4+ T cell responses via antigen presentation, and the release of inflammatory cytokines (e.g., TNF-α and IL-6)." (PMID 38339108, 2024). "Additionally, integrating GFAP into biomarker panels with CRP, IL-6, and ANCA could improve diagnosis and treatment monitoring in autoimmune diseases." (PMID 39459426, 2024). "Despite the different role played by IL-6 in SLE when compared to RA, in consideration of the low number of subjects enrolled, we decided to combine the RA and SLE populations into a single cohort representative of the overall sample of patients affected by autoimmune disease in general." (PMID 38003490, 2023). "Pro-inflammatory factors such as IL-6 or cytokines, which originate from the liver during an attack, could be a reasonable explanation for PRES in AHP, similar to other encephalopathies such as eclampsia, autoimmune diseases or cytotoxic medications." (PMID 36757574, 2023). "However, autoantibody production is not the only problem in B cell-mediated autoimmune diseases, as B cell-derived cytokines such as IL-6 can support autoimmunity." (PMID 36010934, 2022). "Cytokines such as IL-6, IL-23, TGF - β and IL-1 β induce TN cells to differentiate into Th17 cells, mediate the inflammatory response, eliminate bacteria and fungi outside the cells, and are closely related to the occurrence and development of autoimmune diseases." (PMID 33194780, 2020). "IL-21 and IL-6 together could induce CD4+CXCR+PD-1+ Tfh cell differentiation, and this Tfh cells could promote immunoglobulin production form B cells, thus Tfh cells could be a therapeutic target for treatment of autoimmune disease." (PMID 30760702, 2019). "There is no doubt that IL-6 plays an important role in several autoimmune diseases." (PMID 24416448, 2014). "By meta-regression, we observed a significant negative linear relationship between duration and effect size of marine-derived n-3 PUFAs supplementation on IL-6 and TNF-α in subjects with chronic non-autoimmune disease, indicating that longer duration of use could lead to a greater lowering effect." (PMID 24505395, 2014). "Additionally, the specificity of C-reactive protein and inflammatory cytokines (e.g. tumor necrosis factor-α and interleukin-6) for OSAS seems to be low because of the high basal levels of these substances in patients with inflammatory disease, autoimmune disease, and many other diseases." (PMID 23805411, 2013). "But importantly, IL-1β and IL-6, both found to be increased in VERA patients, are known to promote the differentiation of Th17 cells, which in turn secrete IL-17A and IL-22, two cytokines that were elevated in VERA patients and have an essential function in the pathogenesis of autoimmune diseases." (PMID 20961415, 2010). "The increased autoimmune disease observed in IL-6KO mice could be due to an early developmental defect in these mice rather than a lack of IL-6 specifically during the early immune response." (PMID 19587788, 2009). "Furthermore, the biological functions of cytokines such as interleukin-6 (IL-6), type 1 interferon (IFN), and tumor necrosis factor-alpha (TNF-α), which constitute the cytokine storm, have been elucidated by research and clinical practice in autoimmune diseases." (PMID 36609472, 2023).
autoimmune disease (continued). "The overexpression of inflammatory cytokines, such as IL-1, IL-6, IL-18 and calcium binding proteins, as well as the striking response to IL-1 and IL-6 inhibition, have led to postulating that they should be considered complex, polygenic autoinflammatory syndromes, rather than autoimmune diseases." (PMID 35078234, 2022). "Furthermore, capsules around SBIs contain inflammatory cells that are predominantly Th1/Th17 cells, releasing high amounts of IL-6, IL-8, IL-17 and IFN-γ as well as defective regulatory T-cells, which possibly may result in the development of inflammatory/autoimmune diseases." (PMID 35075507, 2022). "In addition, a previous study suggested that IL‐6 or TNF‐α‐activated NF‐κB p65 could bind to miR‐34a promoter and up‐regulate its transcription, which could serve as a novel mechanistic and therapeutic insight into autoimmune disease progression." (PMID 34346538, 2021). "Cumulatively, PGE2 potentiated the suppressive phenotype and functions of GM-CSF/IL-6-induced M-MDSC and changed the mechanisms involved in Treg induction, which could be important for investigating new therapeutic strategies focused on MDSC-related effects in tumors and autoimmune diseases." (PMID 30936876, 2019). "Thus, unlike autoimmune diseases such as RA, IL-6 and TNF-α may not be ideal therapeutic targets of ALS and the elevation of these two cytokines may be due to a secondary event of neuroinflammation rather than a cause of disease." (PMID 27070121, 2016). "As a consequence, treatment of autoimmune diseases with in vitro derived iTregs may not be successful because of limited availability of TGFβ at the target organ or to dominant amounts of inflammatory IL-6." (PMID 26815406, 2015). "Furthermore, chebulanin treatment decreased the expression of the autoimmune disease-related cytokines (TNF-α and IL-6) and enzymes (COX-2 and MMP-3), indicating that the therapeutic mechanism of chebulanin may involve inhibition of inflammatory signaling in the joints of CIA mice." (PMID 26402786, 2015). "Recently, we reported the participation of IL-6 and chemokines in these patients and showed that the levels of practically all the molecules that had originally shown high concentrations decreased significantly, although not as far as the levels found in the patients without autoimmune diseases." (PMID 18836530, 2008). "Interleukin-6 has also been reported to be elevated in patients with IMT, myxoma, and autoimmune diseases, but it was not elevated in our patient." (PMID 37656266, 2023). "Accordingly, although not directly attributed to B cells alone, in numerous autoimmune diseases, such as MS, SLE and RA, serum levels of IL-6 have correlated with disease activity and autoantibody titres." (PMID 36179248, 2022). "In the absence of IL-6 or IL-1β, the TGF-β signaling pathway induces the differentiation of regulatory T cells, which prevent autoimmune diseases by inducing anti-inflammatory cytokines." (PMID 33126239, 2020). "The effect of marine-derived n-3 PUFAs supplementation on CRP, IL-6 and TNF-α in subjects with chronic no-autoimmune disease (data were log-transformed before analysis)." (PMID 24505395, 2014). "Elevated IL-6 and TNF-α levels are not exclusive to GDM and may also be observed in other conditions, such as infections and autoimmune diseases, and also pregnancy-related conditions such as preeclampsia and preterm birth." (PMID 40722699, 2025). "However, it has been reported that Th17 cells induced by IL-6 and TGF-β are not sufficient to elicit autoimmune diseases, which require a co-stimulation of IL-23, or another co-stimulation of IL-6, IL-1β, and IL-23 in the absence of TGF-β9,10." (PMID 37280225, 2023). "Taken together with previous studies by others, current biologic agents including IL-6 blockade and TNF inhibitors, highly efficacious in treating autoimmune diseases, may not work well for treating ALS." (PMID 27070121, 2016).